ATG4D (autophagy related 4D cysteine peptidase)
Description:
[Cysteine protease ATG4D]: Cysteine protease that plays a key role in autophagy by mediating both proteolytic activation and delipidation of ATG8 family proteins. The protease activity is required for proteolytic activation of ATG8 family proteins: cleaves the C-terminal amino acid of ATG8 proteins MAP1LC3 and GABARAPL2, to reveal a C-terminal glycine. Exposure of the glycine at the C-terminus is essential for ATG8 proteins conjugation to phosphatidylethanolamine (PE) and insertion to membranes, which is necessary for autophagy (By similarity). In addition to the protease activity, also mediates delipidation of ATG8 family proteins. Catalyzes delipidation of PE-conjugated forms of ATG8 proteins during macroautophagy. Also involved in non-canonical autophagy, a parallel pathway involving conjugation of ATG8 proteins to single membranes at endolysosomal compartments, by catalyzing delipidation of ATG8 proteins conjugated to phosphatidylserine (PS). ATG4D plays a role in the autophagy-mediated neuronal homeostasis in the central nervous system (By similarity). Compared to other members of the family (ATG4A, ATG4B or ATG4C), constitutes the major protein for the delipidation activity, while it promotes weak proteolytic activation of ATG8 proteins (By similarity). Involved in phagophore growth during mitophagy independently of its protease activity and of ATG8 proteins: acts by regulating ATG9A trafficking to mitochondria and promoting phagophore-endoplasmic reticulum contacts during the lipid transfer phase of mitophagy. [Cysteine protease ATG4D, mitochondrial]: Plays a role as an autophagy regulator that links mitochondrial dysfunction with apoptosis. The mitochondrial import of ATG4D during cellular stress and differentiation may play important roles in the regulation of mitochondrial physiology, ROS, mitophagy and cell viability.
Synonyms: HsAPG4D; APG4D; AUTL4; APG4-D; SPGF101
Tractability: PROTAC: ubiquitination databases record sites on it.
Gene: Protein-coding gene on chromosome 19 (10,543,533 to 10,553,423, forward strand). Ensembl gene ENSG00000130734.
Subcellular location: Cytoplasm (Cysteine protease ATG4D); Cytoplasm (Cysteine protease ATG4D, mitochondrial); Mitochondrion matrix
Subcellular location (Human Protein Atlas): Mitochondria; Nucleoplasm
Pathways (Reactome):
Autophagy: Macroautophagy
Gene Ontology:
Molecular function: cysteine-type peptidase activity; cysteine-type endopeptidase activity; protein-phosphatidylethanolamide deconjugating activity
Biological process: autophagy; mitophagy; protein delipidation; protein localization to phagophore assembly site; proteolysis; aggrephagy; autophagosome assembly; piecemeal microautophagy of the nucleus; protein processing
Cellular component: cytoplasm; mitochondrial matrix; mitochondrion
Genetic constraint (gnomAD): Loss-of-function variants: 51 observed, 53.86 expected, observed/expected ratio (o/e) 0.95, 90% interval 0.75 to 1.2. The upper end of that interval is the gene's LOEUF score, 1.2, which puts it in group 5 of 6, group 1 being the genes least tolerant of losing a copy. Missense variants: 635 observed, 614.36 expected, observed/expected ratio (o/e) 1.03, 90% interval 0.97 to 1.1. Synonymous variants: 268 observed, 251.02 expected, observed/expected ratio (o/e) 1.07, 90% interval 0.96 to 1.18.
Homologues: Orthologues: chimpanzee ATG4D (99% identical), macaque ATG4D (99% identical), dog ATG4D (94% identical), pig ATG4D (93% identical), guinea pig ATG4D (89% identical), rat Atg4d (87% identical), mouse Atg4d (86% identical), rabbit ATG4D (64% identical), zebrafish atg4da (52% identical), tropical clawed frog atg4d (52% identical), Drosophila melanogaster Atg4b (41% identical), zebrafish atg4db (37% identical). Paralogues in human: ATG4C (44% identical), ATG4B (28% identical), ATG4A (25% identical).
Diseases named in the same sentence as ATG4D in open-access papers:
ATG4D is named in the same sentence as 44 diseases in open-access papers, as found by Europe PMC text mining. Sharing a sentence is not in itself a finding about the gene and the disease. The quoted sentences say what the papers report.
breast carcinoma (4 papers, 2017 to 2021). "Autophagy Related 4D Cysteine Peptidase (ATG4D) and its paralog gene ATG4C played an important role as autophagy regulators that linked mitochondrial dysfunction with apoptosis in cancers such as breast carcinoma, human uterine fibroids, colorectal cancer and glioma." (PMID 34238288, 2021). "Suppressed autophagy on the account of miR-101 is reported in breast cancer (targeting RAB5A, STMN1 and ATG4D), HCC (through EZH2) and in ischemic liver (via activating mTOR signaling pathway)." (PMID 32124227, 2020).
colorectal cancer (4 papers, 2018 to 2021). A primary or metastatic malignant neoplasm that affects the colon or rectum. "It has been reported that the low expression of ATG4D was associated with Colorectal Cancer of III stage." (PMID 33604190, 2021). "The expression of ATG4D and MAP1LC3C is low in colorectal cancer, and ATG4D is related to the poor prognosis of pancreatic cancer." (PMID 33604190, 2021).
glioma (4 papers, 2021 to 2025). A benign or malignant brain and spinal cord tumor that arises from glial cells (astrocytes, oligodendrocytes, ependymal cells). "Although the roles of ATG4C and ATG4D in autophagy are less well‐characterized compared to ATG4A and ATG4B, knockdown of ATG4C has been shown to induce cell cycle arrest at the G1 phase and ROS‐mediated apoptosis in glioma cells, likely through suppression of autophagy." (PMID 40883962, 2025).
prostate carcinoma (4 papers, 2020 to 2024). A carcinoma that arises from epithelial cells of the prostate gland. "ATG4D affects the biological behavior of prostate cancer by regulating the activity of androgen receptor." (PMID 33604190, 2021).
cerebellar ataxia (3 papers, 2021 to 2023). A neurological syndrome characterized by clumsy and uncoordinated movement of the limbs, trunk, and cranial muscles. "In Lagotto Romagnolo dogs, a missense mutation in the autophagy-related protein 4 homolog D (ATG4D) gene also on CFA20 is responsible for a vacuolar storage type of cerebellar ataxia." (PMID 36292596, 2022). "All these alterations, which were not sex-biased in any of the performed tests, became more pronounced in aged Atg4d−/− mice, indicating that ATG4D loss leads to progressive cerebellar ataxia, in line with our immuno-histological analyses showing progressive PC demise." (PMID 33795848, 2021).
pancreatic cancer (3 papers, 2021). "The weakened ATG4D-mediated mitophagy dominated by PPARγ might play a role in the process of inhibiting pancreatic cancer cell stemness." (PMID 35186942, 2021). "Meanwhile, the activation of PPARγ might reduce pancreatic cancer cell stemness to improve PDAC chemosensitivity via down-regulating ATG4D." (PMID 35186942, 2021).
breast tumors (2 papers, 2025 to 2026). "On the contrary to our findings, in a previous study on breast tumors, promoter hypermethylation of ATG9A, ATG9B, ATG2B, and ATG4D genes was linked to reduced gene expression." (PMID 40949798, 2025).
gastric cancer (2 papers, 2020 to 2021). A primary or metastatic malignant neoplasm involving the stomach. "The risk score was constructed based on 4 genes (GRID2, ATG4D,GABARAPL2, CXCR4), and gastric cancer patients were significantly divided into high-risk and low-risk groups according to overall survival." (PMID 32477008, 2020).
viral infections (2 papers, 2021 to 2025). "As a key regulator of autophagy, ATG4D influences cellular survival and proliferation, particularly in the context of viral infections." (PMID 40630202, 2025).
cervical cancer (1 paper, 2021). A primary or metastatic malignant neoplasm involving the cervix. "Finally, among the 12 autophagy biomarkers related to the survival of cervical cancer, based on literature search, we selected 6 genes (ATG4C, ATG4D, CD46, TP73, SERPINA1 and HSPB8) to verify their RNA expression in CC and normal cervical tissue samples." (PMID 34238288, 2021). "The experimental results confirm that ATG4D, CD46, TP73 and HSPB8 are decreased in cervical cancer, and the prognosis model shows a negative correlation with the risk score, it could be inferred that they had a protective effect on the occurrence and prognosis of cervical cancer." (PMID 34238288, 2021).
fibroids (1 paper, 2017). "To directly investigate the contribution of ATG4D in the control of cell proliferation, and extracellular matrix production, the two hallmarks of uterine fibroids, we knockdown the expression of ATG4D in normal UTSM myometrial cell line." (PMID 28815060, 2017).
glioblastoma (1 paper, 2024). The most malignant astrocytic tumor (WHO grade IV). "The interaction between SUMOylated FUS and HNRNP D promotes the stability of autophagy-related 4D cysteine peptidase (ATG4D), which inhibits mitochondrial autophagy and suppresses glioblastoma development." (PMID 39366930, 2024).
hepatocellular carcinoma (1 paper, 2024). A malignant tumor that arises from hepatocytes. "In another study on hepatocellular carcinoma, elevated ATG4D expression in tumor tissues was found, and its silencing led to decreased cell proliferation and increased sensitivity to cisplatin." (PMID 38240686, 2024).
invasive ductal carcinoma (1 paper, 2024). "Notably, anomalies in ATG4D promoter methylation and its defective expression have been correlated with a suppression of the autophagy signaling pathway, as evidenced in invasive ductal carcinoma and human uterine fibroids." (PMID 38240686, 2024).
liver fibrosis (1 paper, 2021). "CCl4-induced liver fibrosis in mice resulted in downregulated levels of hepatic mmu_circ_0000623 and when mice were treated with EVs from AD-MSCs enriched in this circular RNA, liver fibrosis was suppressed due to promotion of miR-125/ATG4D-mediated autophagy of damaged cells, including hepatocytes." (PMID 34202136, 2021).
male infertility (1 paper, 2024). The inability of the male to effect fertilization of an ovum after a specified period of unprotected intercourse. "Five recessive mutations in ATG4D have also been potentially associated with male infertility in humans via non-obstructive azoospermia." (PMID 38920354, 2024).
melanoma (1 paper, 2024). A malignant, usually aggressive tumor composed of atypical, neoplastic melanocytes. "In this frame, ATG4D, ATAD3A, and MRPL41 were the top three genes negatively correlated with GALC expression in the TCGA Skin Cutaneous Melanoma database." (PMID 38474307, 2024).
multiple sclerosis (1 paper, 2017). A progressive autoimmune disorder affecting the central nervous system resulting in demyelination. "LYST encodes a lysosomal trafficking regulator whilst ATG4D is a cysteine peptidase involved in autophagy and this locus is associated with multiple sclerosis, psoriasis, and rheumatoid arthritis." (PMID 29059182, 2017).
nasopharyngeal carcinoma (1 paper, 2025). A carcinoma arising from the nasopharyngeal epithelium. "Diagram illustrating the modulation of autophagy initiation by a virus, focusing on the upregulation of ATG4B and ATG4D inhibiting distant metastasis in EBV-associated nasopharyngeal carcinoma." (PMID 40630202, 2025).
osteosarcoma (1 paper, 2025). A usually aggressive malignant bone-forming mesenchymal neoplasm, predominantly affecting adolescents and young adults. "Clinically, elevated ATG4D expression correlates with poorer prognosis in patients with osteosarcoma, highlighting ATG4D as a potential therapeutic target for improving treatment outcomes." (PMID 40883962, 2025). "Further investigation is warranted to clarify the mechanistic contribution of ATG4D to osteosarcoma oncogenesis." (PMID 40883962, 2025). "In this study, we report the following findings: (i) Knockdown of ATG4 family members resulted in cell cycle arrest at the G1 phase and an increase in the subG1 proportion, with the most pronounced effects observed in ATG4D‐silenced osteosarcoma cells." (PMID 40883962, 2025). "ATG4D appears to facilitate autophagy progression to degrade damaged organelles and ubiquitinated cargos in osteosarcoma cells, potentially through its involvement in autophagosome formation and the delipidation of LC3‐II." (PMID 40883962, 2025). "Kaplan–Meier survival analysis indicated that osteosarcoma patients with high ATG4D expression had significantly poorer overall survival (p = 0.026)." (PMID 40883962, 2025). "In vivo, osteosarcoma cells harboring ATG4D‐targeting shRNA exhibited reduced tumor growth and elevated apoptosis in xenografted mice compared to control cells." (PMID 40883962, 2025). "Clinically, ATG4D protein expression was elevated in osteosarcoma tissues compared to normal bone cells, with higher levels correlating with poor overall survival, particularly in patients older than 10 years or with tumors located in the lower limbs." (PMID 40883962, 2025). "Consistent with previous reports, knockdown of ATG4 family members significantly reduced the motility of osteosarcoma cells, particularly in ATG4D‐silenced cells." (PMID 40883962, 2025). "This study suggested that silencing ATG4 family members (ATG4A, ATG4B, ATG4C, and ATG4D) led to an increased proportion of cells in the G1 phase in osteosarcoma cells." (PMID 40883962, 2025). "ATG4D‐silenced osteosarcoma cells exhibited heightened sensitivity to starvation and chemotherapeutic drugs when compared to cells treated with scrambled siRNA; (iv) Silencing ATG4D inhibited tumor formation in xenografted mouse models." (PMID 40883962, 2025). "Tumor volume in mice xenografted with osteosarcoma cells expressing ATG4D‐targeting shRNA exhibited a significant weekly decrease compared to tumors derived from nontarget osteosarcoma cells." (PMID 40883962, 2025). "ATG4D ablation also sensitized osteosarcoma cells to starvation and chemotherapeutic treatments." (PMID 40883962, 2025). "Silencing ATG4D led to a significant increase in caspase‐3/7 activity, which was attenuated by a pan‐caspase inhibitor, indicating that ATG4D depletion induces caspase‐3/7‐mediated death in osteosarcoma cells." (PMID 40883962, 2025). "ATG4D‐mediated autophagy may contribute to cell cycle progression and enhance the migratory capacity of osteosarcoma cells." (PMID 40883962, 2025). "However, further investigation is required to evaluate the specific role of ATG4D protease activity and ATG8ylation in autophagy and drug resistance in osteosarcoma cells." (PMID 40883962, 2025). "Additionally, ATG4D protein expression was found to be elevated in tumor tissues and correlated with poor prognosis in patients with osteosarcoma." (PMID 40883962, 2025). "Similarly, LC3 and the autophagy adaptor protein p62 were upregulated in ATG4D‐silenced osteosarcoma cells, resembling the effects observed upon hydroxychloroquine (HCQ) treatment, an autophagy inhibitor." (PMID 40883962, 2025). "In addition, our study showed a correlation between ATG4D protein levels and poor survival outcomes in patients with osteosarcoma." (PMID 40883962, 2025). "Knockdown of ATG4D significantly reduced its mRNA expression levels in osteosarcoma cells." (PMID 40883962, 2025).
osteosarcoma (continued). "Additionally, ATG4D knockdown enhanced the cytotoxic effects of chemotherapeutic agents, including doxorubicin and oxaliplatin, in osteosarcoma cells." (PMID 40883962, 2025). "Our study suggests that ATG4D plays a crucial role in the tumor malignancy of osteosarcoma." (PMID 40883962, 2025). "However, the role of ATG4D in cancer cell proliferation and drug resistance, particularly in osteosarcoma cells, remains poorly understood." (PMID 40883962, 2025). "Our findings suggest that ATG4D plays a critical role in regulating osteosarcoma progression and may serve as a potential therapeutic target for improving treatment outcomes in osteosarcoma patients." (PMID 40883962, 2025). "Therefore, larger cohort studies are required to further elucidate the prognostic significance of ATG4D in osteosarcoma." (PMID 40883962, 2025). "Notably, these mRNA expression patterns did not fully correlate with the phenotypic effects observed upon gene silencing, implying that ATG4D's functional role in osteosarcoma may depend more on its protein abundance or posttranslational regulation." (PMID 40883962, 2025). "This study revealed that ATG4D knockdown increased LC3B‐II puncta (lipidated LC3) and inhibited autophagy, sensitizing osteosarcoma cells to starvation conditions." (PMID 40883962, 2025). "Moreover, ATG4D depletion enhanced autophagic markers, including LC3B‐II puncta and p62 protein levels, and sensitized osteosarcoma cells to starvation and chemotherapy‐induced cell death." (PMID 40883962, 2025).
ovarian carcinoma (1 paper, 2023). A malignant neoplasm originating from the surface ovarian epithelium. "Kaplan-Meier plot analysis indicated that the expression levels of GSS, KEAP1, ATG3, and ATG4D correlated significantly and negatively with the survival of patients with ovarian cancer." (PMID 37215446, 2023). "Finally, we explored whether factors such as ATF4, GPX4, GSS, KEAP1, NFE2 like BZIP transcription factor 2 (NEF2L2), SLC7A11, SQSTM1, ATG3, ATG4D, and ATG5 have potential as non-invasive diagnostic markers for ovarian cancer." (PMID 37215446, 2023). "The results of multiple gene correlation analyses indicated that there was a significant linear relationship (positive correlation) between the expression of ATF4 in ovarian cancer tissue and the expression levels of GPX4, GSS, KEAP1, NFE2L2, SLC7A11, ATG3, ATG4D, and ATG5." (PMID 37215446, 2023).
sarcoma (1 paper, 2025). A usually aggressive malignant neoplasm of the soft tissue or bone. "Impact of ATG4D expression levels on overall survival by the different demographic and clinicopathologic factors with sarcoma." (PMID 40883962, 2025).